RSKR (ribosomal protein S6 kinase related)
Synonyms: SGK494; FLJ25006
Tractability: Antibody: the Human Protein Atlas places it where antibodies can reach. PROTAC: ubiquitination databases record sites on it.
Gene: Protein-coding gene on chromosome 17 (28,455,752 to 28,614,197, reverse strand). Ensembl gene ENSG00000167524.
Subcellular location (Human Protein Atlas): Plasma membrane; Vesicles; Nucleoplasm
Gene Ontology:
Molecular function: protein binding; protein kinase activity; ATP binding; kinase activity; protein serine kinase activity; protein serine/threonine kinase activity
Genetic constraint (gnomAD): Loss-of-function variants: 44 observed, 59.8 expected, observed/expected ratio (o/e) 0.74, 90% interval 0.58 to 0.95. The upper end of that interval is the gene's LOEUF score, 0.95, which puts it in group 4 of 6, group 1 being the genes least tolerant of losing a copy. Missense variants: 510 observed, 527.61 expected, observed/expected ratio (o/e) 0.97, 90% interval 0.9 to 1.04. Synonymous variants: 181 observed, 197.38 expected, observed/expected ratio (o/e) 0.92, 90% interval 0.81 to 1.04.
Homologues: Orthologues: chimpanzee RSKR (99% identical), macaque RSKR (95% identical), pig RSKR (85% identical), mouse Rskr (84% identical), rat Rskr (83% identical), tropical clawed frog rskr (58% identical), guinea pig RSKR (55% identical), zebrafish rskrb (46% identical), zebrafish rskra (46% identical), Caenorhabditis elegans F31E3.2 (34% identical). Paralogues in human: GRK6 (26% identical), GRK4 (24% identical), GRK5 (24% identical), GRK2 (23% identical), GRK3 (22% identical), GRK1 (22% identical), GRK7 (22% identical).
Diseases named in the same sentence as RSKR in open-access papers:
RSKR is named in the same sentence as 1 disease in open-access papers, as found by Europe PMC text mining. Sharing a sentence is not in itself a finding about the gene and the disease.
RSKR shares sentences with these, for which no sentence is quoted: diabetes (1 paper).